MMP2 (matrix metallopeptidase 2)
Diseases named in the same sentence as MMP2 in open-access papers (continued):
Sharing a sentence is not in itself a finding about the gene and the disease.
breast cancer (continued). "We, and others, have demonstrated that extracellular Hsp90α enhances breast cancer cell invasiveness through MMP-2 activation as well as other client proteins including ErbB2 and plasmin." (PMID 21533148, 2011). "In this study, we show that a complex of co-chaperones outside of breast cancer cells assists Hsp90α mediated activation of MMP-2." (PMID 21533148, 2011). "Differential methylation of the MMP-2 promoter has been reported in the region up to +733 bp from the transcription start site, in a breast cancer cell line." (PMID 21359202, 2011). "Studies of canine mammary tumors suggest that pro-MMP-2 activation requires the formation of a ternary complex that consists of the C-terminal domain of pro-MMP-2, TIMP-2 and MT1-MMP." (PMID 21726449, 2011). "Together, these findings show that Hsp90α forms a complex with Hsp70, Hop, Hsp40, and p23, in addition to MMP-2, both in vitro and in breast cancer cell media." (PMID 21533148, 2011). "It has been shown that elevated serum levels of IL-6 and MMP-2 in breast cancer patients correlates with the stage and the severity of the disease." (PMID 20723242, 2010). "Our present findings demonstrate that both the α and the β isoforms of HSP90 are secreted by cultured MDAMB453 human breast cancer cells and interact with matrix metalloproteinases, MMP2 and MMP9." (PMID 20602761, 2010). "Our results showed that both HSP90α and HSP90β are secreted by MDAMB453 human breast cancer cells and interact with MMP2 and MMP9." (PMID 20602761, 2010). "We assumed that this would also help us to obtain a better understanding of the regulatory effects of monothiol antioxidants (GSH and NAC) on MMP-2 gelatinolytic action in the MCF-7 breast cancer cell line." (PMID 21118526, 2010). "MMP-2 is expressed in the early stages of breast cancer and is believed to contribute to the first events leading to tumour formation because of its ability to degrade the basement membrane." (PMID 20723242, 2010). "Melatonin exerts an inhibitory effect on breast cancer cell invasion through down-regulation of the p38 pathway, and inhibition of MMP-2 and MMP-9 expression and activity." (PMID 21167057, 2010). "And in another study, breast cancers induced by Wnt-1 overexpressed a series of MMPs, including MMP-2 and MMP-9, except MMP-7, a long held Wnt target gene in intestinal tumors." (PMID 19586554, 2009). "This is in accordance with other studies, verifying MMP-2 to be an unfavorable prognostic factor in breast cancer." (PMID 19531263, 2009). "Using Northern Blot analysis, a higher expression of MMP-2, -7, -9 and -11 mRNA was shown in breast cancer tissue in comparison to normal breast tissue." (PMID 19531263, 2009). "Co-regulation of heparanase and MMPs was also noted by a marked decrease in MMP (primarily MMP-2,-9 and 14) expression following transfection and over-expression of the heparanase gene in cultured human mammary carcinoma (MDA-MB-231) cells." (PMID 19360105, 2009). "Elevated levels of both MMP2 and MMP9 have been observed in blood from breast cancer patients and were repeatedly found to be associated with advanced stage, lymph node metastasis and poor prognosis." (PMID 18366705, 2008). "Our observation of increased levels of MMP-2 in the sera of responders supports the notion of matrix metalloproteinase involvement in breast cancer." (PMID 18474099, 2008). "Several studies have evaluated the diagnostic and prognostic value of circulating MMP2 and MMP9 in breast cancer because of their important role in tumour invasion and metastasis." (PMID 18366705, 2008). "For example, the γ2 subunit DIII fragment of laminin-5 can bind to the cell surface of MDA-MB-231 breast cancer cells and upregulate the expression of MMP-2 and -9 resulting in an increase migratory activity." (PMID 17987037, 2007). "Supporting the role of MMP-2, radiation enhancement of breast cancer cell invasion was prevented by an MMP-2 inhibitor." (PMID 17987037, 2007).
breast cancer (continued). "Matrix metalloproteinase-1 was immunohistochemically detected in 88.3% of breast carcinomas, MMP-2 in 42%, MMP-7 in 87.4%, MMP-9 in 74%, MMP-11 in 89.3%, MMP-13 in 73.3%, MMP-14 in 90%, TIMP-1 in 95%, TIMP-2 in 87% and TIMP-3 in 82.3%." (PMID 17848954, 2007). "Using zymography, breast cancers were found to express higher levels of activated MMP-2 than benign lesions and in vitro studies showed that activated MMP-2 only is associated with an aggressive potential in breast cancer cell lines." (PMID 16776850, 2006). "In breast cancer, matrix metalloproteinase (MMP)-2 is a protease produced essentially by stromal cells." (PMID 16776850, 2006). "In a study on 14 patients, Onisto and colleagues report that a high MMP-2/TIMP-2 ratio correlated with lymph node metastases in breast cancer while it predicted a better outcome in another study." (PMID 16776850, 2006). "WDNM1, a putative breast cancer metastasis suppressor, was reduced 26-fold, and the MMP-2 inhibitor, TIMP-3, was also decreased in Comma/PDK1 cells." (PMID 16551362, 2006). "Upregulation of MMP-2 expression after estrogen treatment has been described in breast cancer cell and vaginal tissue samples." (PMID 17010202, 2006). "One group has shown that Hs578T breast cancer cells transfected with COX-2 resulted in the activation of MMP-2." (PMID 16831226, 2006). "The expression of MMPs, particularly the gelatinases (MMP-2 and MMP-9) have been associated with high potential of metastasis in several human carcinomas including breast cancer." (PMID 16831226, 2006). "In our tumor bank, information for MMP-2 was available from 610 breast cancers, from 544 for MMP-14 and from 549 cases for TIMP-2." (PMID 16776850, 2006). "For example, transfection of MCF-10A breast cancer cells with either c-erbB-2 or c-ras resulted in increased expression of MMP-2, whereas transfection of MCF-7 cells with the ets gene PEA-3 led to increased production of MMP-9." (PMID 15054465, 2004). "Consistent with their role in breast cancer progression, high levels of MMP-2 have been found to correlate with a poor prognosis in breast cancer patients." (PMID 14710236, 2004). "This study constitutes the largest material of breast carcinoma published showing the prognostic value of MMP-2." (PMID 14520459, 2003). "MMP-2 is also shown to correlate to shortened survival independent of major prognostic indicators in patients with primary breast carcinoma." (PMID 14520459, 2003). "In this study, intracytoplasmic staining of the protein for MMP-2 was found in 78% of the primary tumours of breast carcinoma, 50% displaying an extensive positivity (>50% of the tumour cells positive; MMP-2++)." (PMID 14520459, 2003). "In this study, we explored the role of MMP-2 as a prognostic factor in breast carcinoma in a large series to be able to show the favourable effect of MMP-2 negativity in poor prognosis subgroup of hormone receptor-negative patients." (PMID 14520459, 2003). "In this study, intracytoplasmic expression of the protein for MMP-2 was found in 78% of the primary tumours of breast carcinoma." (PMID 14520459, 2003). "The ability of rosmarinic acid to inhibit MMP-1, MMP-2, MMP-9, aldose reductase, and CDC25B activity may underlie how rosmarinic acid is able to inhibit the development of breast cancer." (PMID 40176865, 2025). "In breast cancer, lactate modulates cancer cell invasion via the TGFβ1/Smad3/MMP2/9 signaling axis." (PMID 40646747, 2025). "MMP2-selective inhibitors were shown to prevent bone metastasis in breast cancer." (PMID 40035822, 2025). "Our results conclude that MMP2 (rs2285053) is associated with an increased risk of breast cancer, while MMP9 (rs3787268) polymorphisms may be correlated with a reduced risk of breast cancer in Bangladeshi females." (PMID 40735254, 2025). "According to the literature, MMP-2, -3, and -9 may be involved in breast cancer metastasis to the brain." (PMID 40043049, 2025).
breast cancer (continued). "In basal-like breast cancer, we found that a low WWOX/HIF1A ratio is associated with particularly aggressive disease because it promotes EMT via ZEB1 and ADAM9, facilitates ECM remodelling via MMP2 and ITGA1, and enables immune evasion via NOTCH1 and TLR4." (PMID 41007296, 2025). "Similarly, Knockdown of TRPS1, a GATA transcription factor, reduced the ability of breast cancer cells to form VM by downregulating MMP2 and MMP9." (PMID 41400702, 2025). "Additionally, cell surface PGs (SDC1 and SDC4) and MMPs (MMP2, MMP7, MMP9, and MMP14) implicated in breast cancer progression were further included." (PMID 41228316, 2025). "Particularly, gelatinases MMP2 and MMP9 appear highly expressed in breast cancer tissues and are strongly associated with tumor staging and metastasis, particularly driving TNBC metastasis, thereby serving as important biomarkers for assessing prognosis and guiding treatment strategies." (PMID 41228316, 2025). "Therefore, our study aimed to investigate the association between MMP2 (rs2285053) and MMP9 (rs3787268) gene polymorphisms with breast cancer in Bangladeshi females." (PMID 40735254, 2025). "MMP2 and MMP9 have thus been potentially linked to breast cancer cell invasion and metastasis." (PMID 40735254, 2025). "In addition, LDHB KO or treatment with LDH inhibitors in ER- breast cancer cells reduced their motile ability in part through reducing the expression of IL-6, IL-8, and MMP-2." (PMID 40507273, 2025). "Our complex network model, which involves potential molecular and cellular factors in the pathogenesis of breast cancer, indicated that the most impactful factors on the network as a whole were MMP2 and MMP9, with statistically significant results (p = 0.01468)." (PMID 40259907, 2025). "The activity of MMP-2 and MMP-9 in serum or plasma, measured by gelatine zymography, has been shown to distinguish between breast cancer subclassification and various risk factors, predict lymph node metastasis, and evaluate treatment response in breast cancer patients." (PMID 38956273, 2024). "Moreover, the GOBO analysis shows an elevated expression profile of the PTGS2/ESR2/EGFR/JUN/MMP2 genes’ signature in the most aggressive breast cancer subtype (Basal) in breast tumor samples and breast cancer cell lines." (PMID 39707884, 2024). "Moreover, gelatin gel zymography analysis of isolated MMP-2 utilizing breast cancer cells (MDA-Mb-231) indicates a strong and direct interaction between Myr and MMP-2 and blocks breast cancer metastasis by lowering the action of MMP-2 and MMP-9." (PMID 38672151, 2024). "Additionally, naringenin inhibited the growth potential of MDA-MB-231 breast cancer cells and downregulated the MMP-2 and MMP-9 expression by binding to Integrin β3, thereby blocking breast cancer cell movement and invasion." (PMID 39572023, 2024). "In addition to being a member of the MMP family, MMP2/9 plays a significant role in the development and progression of various malignancies, particularly ovarian and breast cancers." (PMID 38305998, 2024). "CAF derived lactate may also have other functions such as maintaining increased mitochondrial activity and oxidative phosphorylation in PCa cells, and activating the TGF-β1/p38 MAPK/MMP2/9 pathway to promote invasion in breast cancer cells." (PMID 38584702, 2024). "Prior research highlighted GATA4’s potential to reduce MMP2 expression in breast cancer cells." (PMID 38653973, 2024). "Indeed, the presence of CXCL1 significantly increased breast cancer 4T1 cell migration and invasiveness ability, matrix metalloproteinase-2 (MMP-2) and MMP-9 secretion, as well as the expression of EMT-related proteins in vitro." (PMID 38397187, 2024). "Furthermore, isorhamnetin exhibited inhibitory effects on breast cancer cell proliferation by down-regulating MMP2 and MMP9 protein expression levels." (PMID 39045282, 2024).
breast cancer (continued). "Furthermore, prolonged exposure to cadmium was found to induce migration and invasion of breast cancer cells via the TGIF/MMP2 signaling pathway." (PMID 38807590, 2024). "In a previous finding, Rab27B regulated the release of HSP90 enriched exosomes from metastatic breast cancer cells to activate matrix metalloproteinase 2 (MMP2), thereby degrading the components of ECM and facilitating the secretion of growth factors leading to invasion." (PMID 37006229, 2023). "Analysis performed in a cohort of over one thousand breast cancer patients showed that Crp2 expression positively correlates with expression of inflammatory genes such as the Urokinase plasminogen activator surface receptor (uPAR), Mmp-2 and Mmp-14." (PMID 38173933, 2023). "Intriguingly, extracellular Hsp70 forms an activation complex with different Hsps, including Hsp90α, Hsp70/Hsp90 organizing protein (Hop), and Hsp40, which together enhance the invasion and migration of the breast cancer cells via the upregulation of metalloproteinase-2 (MMP2)." (PMID 36899836, 2023). "Previous studies have shown that the inhibition of S100A4 could inhibit the invasion ability of breast cancer cells through EMT and regulate MMP2 in breast cancer to participate in EMT." (PMID 37033662, 2023). "Quiescent cancer cells with the potential of recurrence form a comfortable environment of fibrillar fibronectin matrix via integrin, ROCK and transforming growth factor β2 (TGF-β2) pathways, whereas an outgrowth would be started by MMP-2-mediated ECM degradation in breast cancer." (PMID 36906534, 2023). "Organophosphorus pesticide exposure enhanced the protein expression of EMT associated proteins vimentin, ax1, and slug, while chlorpyrifos (CPF), one of the most frequently used pesticides around the world, increased MMP2 and vimentin expression driving breast cancer invasion." (PMID 37511154, 2023). "Similarly, CpG hypermethylation at MT1-MMP (MMP-14) and MMP-2 promoter sites decreased the migration of MCF-7 breast cancer cells." (PMID 38069210, 2023). "Quercetin could inhibit the proliferation and invasion of breast cancer cells by downregulating the expression of MMP2 and MMP9." (PMID 35379271, 2022). "Thus, this study found that orosmucoid 1 upregulation in breast cancer cells increased MMP-2 and MMP-9 expression, activated Akt/ERK signaling pathways, all of which stimulating epirubicin resistance via apoptosis inhibition." (PMID 35586209, 2022). "Resveratrol showed a dose-dependent inhibition of TGF-β1-induced EMT-induced cell migration in the human MDA231 breast cancer cell line, decreased the expression levels of MMP-2 and MMP-9, and effectively inhibited MDA231 human breast cancer lung metastasis of cancer." (PMID 36686745, 2022). "Additionally, the expression of RAB27b is correlated with lymph node metastasis in ER+ breast cancer patients as it promotes the secretion of HSP90α, where HSP90α acts as a chaperone that prompts MMP-2 cleavage and activation." (PMID 35563790, 2022). "Similarly, MMP-2 (also referred to as gelatinase A) has been found to be responsible for the invasion and metastasis of malignant melanoma and other cancers, such as breast cancers." (PMID 36140359, 2022). "Our results from the qRT-PCR study revealed that knockdown of expression of LncRNA MAFG-AS1 in breast cancer cells could suppress the expression of MMP2 protein." (PMID 35513366, 2022). "Formononetin as anti-invasive agent for breast cancer, could inhibits migration and invasion of breast cancer cells by suppressing MMP-2 and MMP-9 through PI3K/AKT signaling pathways." (PMID 35922850, 2022). "Decreased expression and proteolytic activity of MMP-9 and MMP-2 were observed in breast tumors after NC-based treatment, suggesting that treatment with NC at a low concentration inhibits breast cancer cell metastasis by suppressing the Src/FAK signaling pathway." (PMID 36362132, 2022).
breast cancer (continued). "Notably, similar to MMP-1, these studies showed that tumoral MMP-2 promotes breast cancer metastasis to the brain." (PMID 36741729, 2022). "The qPCR analysis demonstrated that the synthesized nanoparticles desirably affected the gene expression in the studied breast cancer cell lines; resulting in down-regulation of the MMP-2, MMP-9, cyclin D, and cyclin E while up-regulation of caspase-3 and caspase-9." (PMID 35875198, 2022). "Tumoral MMP-2 enhanced tumor growth and metastasis in an orthotopic mouse model of breast cancer." (PMID 36741729, 2022). "In addition, SETD3 regulates the expression of multiple breast-cancer-associated genes, such as ACTB, FBXW7, Fascin, eNOS, and MMP-2, which suggests it as a promising biomarker for breast cancer prognosis." (PMID 35912180, 2022). "Furthermore, HSP70, together with HSP90, activates matrix metalloproteinase 2 (MMP‐2), thereby increasing the migration and invasion of breast cancer cells." (PMID 35928554, 2022). "Interestingly, in a recent study MMP2 was also seen in both lobular carcinoma in situ (LCIS) and paired normal breast tissue." (PMID 35205651, 2022). "Furthermore, ST3Gal-III modulated breast cancer cell adhesion and invasion by altering sLex expression, E-selectin binding capacity, and invasion-related protein expression including β1 integrin, MMP-2, and MMP-9." (PMID 34577144, 2021). "On the other hand, the expression of MMP-2 tended to be lower in breast carcinoma against that in normal tissues, with a fold change of -3.514, as suggested by in vitro studies, while MMP-2 and MMP-9 were highly expressed in breast cancer tissues and associated with worsening prognosis." (PMID 34181339, 2021). "In the MCF-7 breast cancer cell line, Kae inhibits the protein expression of epithelial-mesenchymal transition-related markers and suppresses metastasis-related markers such as MMP-2 and MMP-9." (PMID 33498927, 2021). "A report on breast cancer cells in culture finds that these cells entering dormancy form a fibrillar fibronectin matrix and exits from dormancy require MMP‐2‐mediated fibronectin degradation, suggesting that stiff fibronectin matrices surrounding the tumor cells promote breast cancer dormancy." (PMID 33754478, 2021). "Furthermore, it has been reported that hypoxia, by HIF1α, induces MMP2 expression in endothelial cells, cardiac fibroblasts, macrophages, and breast cancer cells." (PMID 34359789, 2021). "Moreover, down-regulation of S100A4 in breast cancer cells decreased EMT by suppressing the expression of MMP2." (PMID 33549040, 2021). "In the case of breast cancer metastasis, MMP-2 & 9 play a pivotal role and our study showed the polyphenolic compounds from CP extract were directly and through modulation of the extracellular profile has influenced the MMP-2 expression in MDA-MB-231 negatively." (PMID 34122605, 2021). "Similar to MMP9, MMP2 also increases the invasion of breast cancer cells." (PMID 33832499, 2021). "Therefore, in this study, we also detected the effect of MTDH on Gem-treated breast cancer cells and the expressions of MMP-2 and MMP-9 proteins." (PMID 34552061, 2021). "Evaluation of breast cancer patients and clinical data indicated that GABARAP was associated with the clinicopathology-related characteristics of malignancy and negatively correlated with the expression of MMP2 and MMP14." (PMID 33591943, 2021). "Additionally, Rab40b functions as a regulator in the transport of MMP2/9 during invadopodia formation in breast cancer." (PMID 34141705, 2021). "Functionally, chondroitin polymerizing factor acts as an oncogene that promotes breast carcinoma cell progression by facilitating proliferation, invasion and migration, as well as by elevating the expression of matrix metallopeptidase 2 and epithelial–mesenchymal transition‐related markers." (PMID 33301643, 2021).